AHR (aryl hydrocarbon receptor)
Diseases named in the same sentence as AHR in open-access papers (continued):
Sharing a sentence is not in itself a finding about the gene and the disease.
skin inflammation (continued). "AHR signaling, and its subsequent influence on the expression of genes related to the immune response, is known to play a significant role in the pathogenesis of skin inflammation." (PMID 39337637, 2024). "PAH-activated AhR may further induce skin inflammation via the heightened production of pro-inflammatory cytokines from epidermal keratinocytes such as IL-1α and IL-8." (PMID 37445680, 2023). "Tapinarof is a natural AhR agonist used to treat skin inflammation in humans." (PMID 35625824, 2022). "Tapinarof is a novel, first‐in‐class, small molecule topical therapeutic aryl hydrocarbon receptor (AhR)‐modulating agent that binds and activates AhR, reduce skin inflammation, normalize the skin barrier, reduce oxidative stress and regulate gene expression in immune cells." (PMID 36226669, 2022). "Dioxin, one of the ligands of AhR, has been reported to induce skin inflammation in vivo." (PMID 35625824, 2022). "However, topically applied FICZ reduced inflammation in skin lesions in a murine dermatitis model by AhR activation." (PMID 33499346, 2021). "In addition, in mouse models the AhR gene silencing exacerbates skin inflammation with upregulated gene expression of IL-22, IL-17a, and IL-23." (PMID 34944067, 2021). "Furthermore, topical application of IAId alleviated skin inflammation in a mouse model of AD in an AHR-dependent fashion." (PMID 34831399, 2021). "Moreover, the chemical inhibitor of AHR (CH-223191) was effective in the control of skin inflammation induced by intradermal administration of IL-23, blocking the secretion of IL-22 by Th17 and dermal γδ T cells." (PMID 34831399, 2021). "In general, AhR deficiency in non-hematopoietic cells exacerbates skin inflammation." (PMID 35625824, 2022). "IAId can also activate aryl hydrocarbon receptor (AhR), producing indoleamine 2,3-dioxygenase (IDO) and IL-10 in Langerhans cells (LCs), and thus negatively regulate skin inflammation." (PMID 36939800, 2022). "Using the model of IL-23-induced skin inflammation, we demonstrated that CD69 expression controls AHR-mediated IL-22 expression in Th17 and γδ T cells." (PMID 34831399, 2021). "The present study demonstrated that in an IMQ-induced psoriatic mouse model, AHR activation through TCDD inhibited autophagy-related factor expression in lesional skin and subsequently aggravated skin inflammation clinically as well as molecular changes." (PMID 33921372, 2021). "Rapamycin reduced the aggravated skin inflammation induced by TCDD and restored TCDD-induced autophagy suppression and the increase of AHR expression, oxidative stress, and inflammatory response in the skin lesions of a psoriatic mouse model." (PMID 33921372, 2021).
depression (24 papers, 2018 to 2026). "In association with immune/inflammatory diseases, an increased AHR level appears in patients with major depression and multiple sclerosis." (PMID 36732752, 2023). "The heightened levels of stress and depression in these high-risk conditions, as well as stress/depression per se, will also increase kynurenine activation of the AhR." (PMID 32867244, 2020). "We have recently demonstrated that AHR is associated with inter-individual variation in the plasma KYN concentration in major depressive disorder (MDD) patients and that variation in the KYN concentration was also associated with MDD severity." (PMID 30513921, 2018). "Importantly, these protective effects were remarkably counteracted in aryl hydrocarbon receptor knockout (AhR KO) mice, underlining the key roles of microbiota-indoles-AhR signaling in Meth-associated depression and anxiety." (PMID 39996473, 2025). "AHR is a physiological regulator of myelination and inflammatory processes in the developing central nervous system, implicated in psychiatric disorders like major depressive disorder." (PMID 37542243, 2023). "A gut microbe–indoles–AhR–neurogenesis-mediated signalling pathway could thus underlie the alleviation of depression." (PMID 36501051, 2022). "Moreover, germ-free mice exhibit a deficiency in AhR agonists and show increased susceptibility to chronic stress and anxiety and depression-like behavior." (PMID 32957545, 2020). "Additionally, indole with derivatives also originating from Trp have also been demonstrated to be ligands for AHR and, via immune-related pathways and restorative neurogenesis timing, linked to the pathogenesis of depression." (PMID 33139656, 2020). "Having confirmed the effects of indole derivatives and the AhR signaling pathway on Meth-induced behavioral abnormalities, then we sought to investigate the impact of these molecules on microglial morphology and neurogenesis, which are closely associated with depression and anxiety." (PMID 39996473, 2025). "Collectively, these findings propose a novel therapeutic strategy for UC and associated depression, highlighting SCP's potential value in targeting the Trp metabolism-AhR axis." (PMID 41800260, 2026). "Lastly, our study focused on the role of indole derivatives and AhR activation in Meth withdrawal-related anxiety and depression." (PMID 39996473, 2025). "This study’s findings suggest that the alleviation of the pain–depression comorbidity by sEH inhibitors occurs via distinct signaling pathways involving TSPO or AHR." (PMID 36732752, 2023). "AhR modulates depression-like behavior, and AhR antagonism ameliorates depression-like behavior induced by LPS." (PMID 37593014, 2023). "While there are many ways in which inflammation and the microbiome can interact in depression, a microbiome-responsive regulator of the immune system called the aryl hydrocarbon receptor (Ahr) has the potential to serve as a lynchpin in this pathway." (PMID 35597802, 2022). "While these SNPs were not genome-wide significant, functional studies, as described subsequently, demonstrated that both DEFB1 and AHR played important roles in mediating inflammatory pathways that are involved in depression." (PMID 33510640, 2020). "Contrary, pharmacological inhibition of AhR and circulatory monocyte clearance decreased levels of LPS and Kyn and reduced the depressive symptoms in mice, indicating that Kyn and AhR are critical for immunoregulation and depression." (PMID 32957545, 2020). "This study isolated a novel low-molecular-weight Schisandra chinensis polysaccharide (SCP) that ameliorated UC and comorbid depression by remodeling gut microbiota, redirecting tryptophan (Trp) metabolism toward the indole pathway, and activating aryl hydrocarbon receptor (AhR)." (PMID 41800260, 2026). "Modulation of AhR signaling could be a valuable approach to alleviate the comorbidity of chronic pain and depression." (PMID 36232555, 2022).
depression (continued). "AhR provides a potential therapeutic target for treating depression induced by chronic pain." (PMID 36232555, 2022). "This suggests that AHR signaling in the ileum could be contributing to the neuroinflammatory phenotype in the brain characteristic of chronic and recurrent stress-induced depression." (PMID 34248950, 2021). "However, there is a growing appreciation that even classical psychiatric disorders—such as depression, anxiety, and schizophrenia —are powerfully determined by alterations in the kynurenine pathway and the AhR regulation of the immune system." (PMID 32867244, 2020). "sEH underlies the mechanisms of the comorbidity of chronic pain and depression and that TPPU exerts a beneficial effect on anhedonia behaviors in a pain model via AHR and TSPO signaling." (PMID 36732752, 2023). "In UCRS mice, deletion of CD4-specific AHR or RORγt does not influence behaviors that resemble anxiety or depression." (PMID 39655201, 2024). "This suggests that AHR signaling is involved exclusively in the occurrence of depression-like symptoms and explains why AHR expression in the spinal cord was not different between the anhedonia-susceptible mice and the sham group." (PMID 36732752, 2023). "In addition to synergistically promoting depressive symptoms with AHR, sEH can also inhibit normal TSPO function by inducing the co-occurrence of pain and depression." (PMID 36732752, 2023). "AHR or RORγt genetic impairment in CD4+T cells does not eliminate depression vulnerability in UCRS mice, whereas neutralization of RORα and RORγt may prevent depression in UCRS rats." (PMID 39655201, 2024).
non-small cell lung carcinoma (24 papers, 2015 to 2024). A group of at least three distinct histological types of lung cancer, including non-small cell squamous cell carcinoma, adenocarcinoma, and large cell carcinoma. "Nuclear AhR expression is significantly associated with poor survival of patients with non-small cell lung carcinoma." (PMID 38807762, 2024). "Further, the stabilization and activation of AhR has been associated with the expression of deubiquitinase UCHL3 promoting cancer stemness in non-small cell lung carcinoma." (PMID 37696458, 2023). "AHR levels are inversely proportional to the autophagy potential in non-small cell lung cancer cells; the activation of AHR causes less metastatic potential by downregulating autophagy, resulting in lesser EMT progression." (PMID 33562118, 2021). "Exploring how modulation of the AHR protein levels may alter cancer stem cell-like properties and associated gene expression can be insightful since overexpression of AHR has been implicated in an aggressive tumor phenotype in non-small cell lung cancer." (PMID 37894798, 2023). "Nuclear localization of AhR was correlated with the worst outcomes for patients with non-small cell lung cancer." (PMID 38518996, 2024). "Consistently, AhR inhibition or knockdown sensitizes non-small cell lung cancer to EGFR tyrosine kinase inhibitors in vitro and in vivo." (PMID 38807762, 2024). "This study provides new evidence that AhR plays an important role in non-small cell lung cancer development." (PMID 37056388, 2023). "UCHL3 maintains AhR protein stability and thereby confers cancer stem-like properties to non-small cell lung cancer cells, functioning as a tumor promoter." (PMID 37740194, 2023). "UCHL3 maintains aryl hydrocarbon receptor (AhR) protein stability and confers cancer stem-like properties to non-small cell lung cancer cells, functioning as a tumor promoter." (PMID 37740194, 2023). "The AhR agonist BaP increased PD-L1 (B7-H1) expression in non-small cell lung cancer cells; this impact was AhR-dependent and was reduced by the AhR antagonists CH223191 and ANF." (PMID 37241719, 2023). "Recently, Fang and colleagues demonstrated that IDO1 regulates expression of ADAM metallopeptidase domain 10 (ADAM10) via IDO1-Kyn-AhR pathway in non-small cell lung cancer (NSCLC) cells and that the induction of ADAM10 downregulates the NKG2D Ligand (NKG2DL)." (PMID 37876966, 2023). "In conclusion, we demonstrated that AhR inhibits iron-dependent cell death (i.e., ferroptosis) in human non-small cell lung cancer cells by binding to the promoter region of SLC7A11, a transcription factor." (PMID 37056388, 2023). "Aryl hydrocarbon receptor (AhR) expression varies among non-small cell lung cancers (NSCLCs), and the mechanisms that support abnormal AhR expression in CSCs remain elusive." (PMID 32546741, 2020). "In the present study, we found that AhR-regulated autophagy positively modulates EMT in non-small cell lung cancer cells." (PMID 28195146, 2017). "Interestingly, the expression patterns of AhR were categorized into three clusters based on the cancer type, with high AhR expression levels being found in regulatory T cells (Tregs) in non-small cell lung cancer (NSCLC)." (PMID 38680496, 2024). "Moreover, UCHL3 in non-small cell lung cancers promotes stem-like characteristics and potent tumorigenic capacity by deubiquitinating the aryl hydrocarbon receptor." (PMID 38474064, 2024). "For example, the mRNA or protein of AhR and its downstream genes were found overexpressed in breast cancer, non-small cell lung cancer, thyroid cancer, cutaneous squamous-cell carcinoma, oral squamous cell carcinoma, pancreatic cancer, endometrial cancer, and meningioma." (PMID 38518996, 2024). "However, higher AhR activity has been suggested as being correlated with increased aggressiveness and a poor prognosis in non-small-cell lung cancer." (PMID 29487603, 2018).
non-small cell lung carcinoma (continued). "Additionally, AHR drives non-small cell lung cancer tumorigenesis when the AHR protein is stabilized after deubiquitination by ubiquitin carboxy-terminal hydrolase isozyme L3, and this AHR action of cancer tumorigenesis may involve Jak2/STAT3 signaling." (PMID 37894798, 2023). "AhR has also been shown to inhibit tumor growth and suppress the expansion of lung progenitor cells in a murine model of KRASG12D-induced non-small cell lung cancer." (PMID 38807762, 2024). "AhR, activated by kynurenine-tryptophan metabolized product by TDO2, bypasses EGFR to retrieve PI3K/AKT and MEK/ERK pathway leading to resistance to tyrosine kinase inhibitors in non-small cell lung cancer." (PMID 34174844, 2021). "In non-small cell lung cancer cells, in the absence of agonist ligands, resting AhR expression is predominantly cytoplasmic and acts as an epithelial mesenchymal transition (EMT) suppressor via a non-genomic pathway." (PMID 30813617, 2019).
allergic disease (23 papers, 2007 to 2026). An immune response that occurs following re-exposure to an innocuous antigen, and that requires the presence of existing antibodies against that antigen. "In addition, in a model of cockroach allergen-induced allergy, mice deficient for AhR in type II alveolar epithelial cells had increased airway hyperreactivity including eosinophilia and elevated Th2 cytokine secretion due to dysregulated autophagy." (PMID 37190854, 2023). "Additionally, tranilast, an anti-allergy drug, has been shown to cause significant upregulation of microRNA (miR)-302 by activation of the AhR." (PMID 24747651, 2014). "Thus, AhR activation may potentially result in enhanced susceptibility to infection or cancer and might trigger autoimmune disorders and allergies." (PMID 35203386, 2022). "At the same time, AHR plays a regulatory role in mediating innate and adaptive immune responses against various infectious diseases, metabolic disorders, cancers, and allergic diseases." (PMID 41511918, 2026). "reviewed AHR and found that AHR plays an important role in allergic diseases and has a significant impact on the expression and control of mast cells, B-cells, macrophages, antigen-presenting cells (APCs), the Th1/ Th2 cell balance, and Th17." (PMID 41511918, 2026). "The AhR has been and still is intensively investigated as a potential therapeutic target in several immunological disorders, including allergic diseases." (PMID 38915403, 2024). "In allergic diseases, targeting the AhR with respective ligands has been shown to inhibit Th2 cell differentiation, reduce the Th2 response, and suppress disease progression in a murine model of atopic asthma." (PMID 38915403, 2024). "Further study of AHR in AD will help clarify to what extent this environmental sensor can regulate responses to allergic disease." (PMID 38344408, 2024). "Further study is needed to put AHR ligand exposures into context, though it is intriguing to consider AHR as a key piece of the environmental puzzle of AD and the rising incidence of other allergic diseases." (PMID 38344408, 2024). "Our work identifies an essential role for homeostatic activation of AhR by dietary ligands in the dampening of cutaneous allergic responses and uncovers the importance of the gut–skin axis in the development of allergic diseases." (PMID 37190854, 2023). "Meanwhile, we believe that understanding the role of AhR in immune responses will enhance our knowledge of AhR-mediated immune regulation in allergic diseases." (PMID 36601108, 2022). "Meanwhile, the role of AhR in regulating the inflammatory effects of environmental pollutants and allergens makes it an attractive target for achieving therapy against allergic diseases." (PMID 36601108, 2022). "Following HDM-induced allergy, ECs from AhR-/- showed a strongly altered gene expression profile, contrarily to CYP1B1-/-, which showed only low DEGs compared to WT with and none without allergy." (PMID 35734174, 2022). "In the context of allergic diseases, ablation of the AhR has been shown to increase the severity of allergic inflammation, indicating a rather protective role of the AhR in these settings." (PMID 35734174, 2022). "In a model of the ovalbumin-induced allergic disease model, it was studied that AhR regulates the differentiation of T cells by dendritic cells." (PMID 36601108, 2022). "Activation of AhR by naringenin (a flavonone) commonly found in grapefruit promoted the differentiation of Tregs in murine models of allergy." (PMID 34249001, 2021). "In an allergy model, DCs isolated from the lungs of AhR-/- mice were able to stimulate greater T cell responses to specific antigen in vitro and showed higher expression of CD86 and MHCII compared with wildtype DCs." (PMID 33339195, 2020).